MORC2 (MORC family CW-type zinc finger 2)
Diseases named in the same sentence as MORC2 in open-access papers (continued):
Sharing a sentence is not in itself a finding about the gene and the disease.
Glucose intolerance (1 paper, 2022). Glucose intolerance (GI) can be defined as dysglycemia that comprises both prediabetes and diabetes. "A recent study demonstrated that MDM2 haploinsufficient in adipocytes induced overt obesity, glucose intolerance, and hepatic steatosis through a novel interplay with the transcriptional cofactors MORC Family CW-Type Zinc Finger 2 (MORC2) and LIPIN1." (PMID 35747386, 2022).
hypopituitarism (1 paper, 2024). A condition of diminution or cessation of secretion of one or more hormones from the anterior pituitary gland. "This is common in patients with MORC2 variants, but extremely rare in cases of congenital hypopituitarism, which further supports the link between variant and phenotype." (PMID 38822427, 2024).
Leigh syndrome (1 paper, 2021). "Herein, we report the case of a patient with clinical manifestations similar to those of Leigh syndrome and a de novo MORC2 gene mutation, c.1079A>G (p.E360G), that was not carried by the parents." (PMID 34664855, 2021).
lung adenocarcinoma (1 paper, 2023). A carcinoma that arises from the lung and is characterized by the presence of malignant glandular epithelial cells. "For example, 3′UTR shortening of MORC2 is also reported in lung adenocarcinoma in which MORC2 mRNA level is elevated." (PMID 37737260, 2023).
neuroblastoma (1 paper, 2022). Neuroblastoma (NB) is the most common solid, extracranial childhood tumor. "Here, to evaluate the pathogenicity of MORC2 variants of unknown significance, we have developed an in vitro system based on the overexpression of wild‐type (WT) or mutant MORC2 proteins in a neuroblastoma cell line SH‐EP and in primary cortical neurons." (PMID 35904125, 2022). "Here we report the characterization of an in vitro model to evaluate the pathogenicity of variants of unknown significance based on MORC2 overexpression in a neuroblastoma cell line SH‐EP or cortical neurons." (PMID 35904125, 2022).
ovarian insufficiency (1 paper, 2020). "Interestingly, a set of 5 proteins (KHDC3L, SRSF8, PNO1, RASIP1, and MORC2) exhibited a significant association with ovarian insufficiency in this cohort." (PMID 32410729, 2020).
schizophrenia (1 paper, 2022). A major psychotic disorder characterized by abnormalities in the perception or expression of reality. "The HUSH- and MORC2-dependent L1 silencing mechanism needs to be explored in the schizophrenia patient-derived cells." (PMID 35832186, 2022).
sensory impairment (1 paper, 2021). "The SNAP amplitude is decreased and the SNCV is slowed concomitant with the sensory impairment in human patients with MORC2 mutation." (PMID 34695197, 2021).
cancer (35 papers, 2011 to 2025). A tumor composed of atypical neoplastic, often pleomorphic cells that invade other tissues. "MORC2, a chromatin remodeler involved in epigenetic silencing and DNA repair, is linked to cancer and neurological disorders when dysregulated." (PMID 40593625, 2025). "Further, MORC2 overexpression is associated with several cancers, including breast, gastric and liver cancers." (PMID 40593625, 2025). "MORC2 expression is linked to several cancers, including breast, gastric, liver and colorectal cancers." (PMID 40593625, 2025). "The present review provides an updated overview of MORC2 in the aspect of cancer hallmark and therapeutic resistance and summarizes its upstream regulators and downstream target genes." (PMID 37692502, 2024). "A key member of the MORC chromatin remodeler family of proteins, MORC2 controls the expression of target genes linked to human cancer and neurological diseases." (PMID 37892209, 2023). "The mutation of MORC2 protein consists in substitution of methionine to isoleucine at residue 276 (M276I), a cancer-associated mutation, which enhances the interaction of MORC2 with hnRNPM." (PMID 38106992, 2023). "This increased expression of MORC2 is linked to cancer cell proliferation, metabolism, invasion, migration, and metastasis and confers chemotherapy resistance." (PMID 37892209, 2023). "To further investigate the role of MORC2 phosphorylation and explore the underlying mechanism in cancer cells, we performed flow cytometry analysis using these stable expressing MORC2 (WT, SA and SE) SGC-7901 cells." (PMID 25888627, 2015). "Therefore, MORC2 has become a new player and promising therapeutic target and is considered a potential diagnostic and therapeutic biomarker of cancer." (PMID 37692502, 2024). "According to TCGA data, the mutation frequency of MORC2 is relatively high in some cancers." (PMID 37692502, 2024). "Additionally, MORC2 associates with transcription factors or histone deacetylases (HDACs) to coordinate the expression of target genes implicated in metabolism and cancer progression." (PMID 37892209, 2023). "Consequently, dysregulation of MORC2 has been linked with the development of multiple types of human cancer and several genetic disorders 24, 31-34." (PMID 36793866, 2023). "In our previous study, we found that MORC2 may act as a transcriptional repressor and play a role in cancer, which promoted us to identify the target gene of MORC2 underlying the mechanism in cancer." (PMID 26098774, 2015). "In our previous study, we found that MORC2 may act as a transcriptional repressor and play a role in cancer, which promoted us to identify the underlying mechanism in cancer." (PMID 25888627, 2015). "Here, we report an in vitro reconstitution of full-length MORC2, the most commonly mutated MORC member, linked to various cancers and neurological disorders." (PMID 40593625, 2025). "These pan-cancer observations suggest that the PGK1/MORC2 pathway represents a shared mechanism of radioresistance across multiple solid tumors." (PMID 41213904, 2025). "The cBioportal web tool was used to retrieve The Cancer Genome Atlas (TCGA) cancer data, and it was found that MORC2 was up-regulated in most tumor samples compared with paired normal tissues, exerting its oncogenic activity in various cancers." (PMID 37692502, 2024). "Conversely, c-Myc can bind to the MORC2 promoter to regulate its expression in cancer cells at high glucose concentrations." (PMID 37692502, 2024). "In the present review, we highlight the role of MORC2 in cancer and provide an outlook on its future in cancer therapy." (PMID 37692502, 2024). "Increasing evidence confirms that some regulators of biosynthesis (e.g., protein kinase and non-coding RNA/ncRNA) play an important role in cancer progression by regulating MORC2." (PMID 37692502, 2024).
cancer (continued). "Antagonizing the effects of forced YAP expression in YAPoff cancer contrasts the role of MORC2 in hepatocarcinoma, a YAPon cancer, in which it represses NF2 and KIBRA to promote YAP activity." (PMID 39172021, 2024). "MORC2 facilitates cancer progression by regulating some aspects of cancer hallmarks demonstrated in cell proliferation, invasion, and migration, as well as cell metabolism." (PMID 37692502, 2024). "Cancer cells treated with a high glucose concentration induce the expression of MORC2, which interacts with c-Myc and gets recruited onto the LDHA promoter to increase the transcription of LDHA." (PMID 37892209, 2023). "MORC2, a poorly defined oncoprotein, is markedly upregulated in most tumour tissues and promotes cancer cell growth, metastasis and drug resistance." (PMID 36967563, 2023). "It was discovered that MORC2 alters the metabolism of cancer cells by regulating glucose metabolism and lipogenesis." (PMID 37892209, 2023). "MORC2 promotes cancer cells’ growth, invasion, and migration by regulating the expression of genes involved in these processes." (PMID 37892209, 2023). "Collectively, these findings unveil a previously unrecognized function and regulatory mechanism of MORC2 in mitotic progression and resistance of cancer cells to MTAs." (PMID 36967563, 2023). "In this review, we emphasize the current developments in our knowledge of MORC2’s role as a transcriptional regulator, its post-translational modifications (PTMs), and its functions in regulating hallmarks of cancer." (PMID 37892209, 2023). "Upon treatment with PTX and VCR, MORC2 degradation helps in prolonged mitotic arrest and the death of cancer cells." (PMID 37892209, 2023). "In the nucleus, MORC2 interacts with the transcription factor c-Myc to control the transcription of genes involved in glucose metabolism to drive cancer cell migration and invasion." (PMID 37892209, 2023). "It is exciting to know that MORC2 plays a crucial role in cancer metabolism, specifically in lipogenesis and glucose metabolism." (PMID 37892209, 2023). "More importantly, MORC2 was upregulated in multiple types of cancer, with posttranslational modification previously regarded as being responsible for MORC2 upregulation." (PMID 37737260, 2023). "Several cancers, including breast, lung, liver, prostate, stomach, colon, ovarian, pancreatic, and endometrial, have dysregulated MORC2 expression." (PMID 37892209, 2023). "Overall, this review concisely summarizes the current knowledge about MORC2-regulated molecular pathways involved in cancer." (PMID 37892209, 2023). "Post-translation modification (PTM) plays an important role in regulating distribution of MORC2 function(s) in DNA damage response and cancer development." (PMID 37892209, 2023). "In this review, we outlined several transcriptional regulatory functions of MORC2 and post-translational modifications of MORC2 and their relevance to cancer." (PMID 37892209, 2023). "It is well reported that MORC2 plays an essential role in invasiveness and metastasis in most types of cancers." (PMID 36234785, 2022). "MORCs, including MORC1, MORC2, MORC3, and MORC4, are linked to immunological disorders, neurogenic disorders, and cancer." (PMID 36142569, 2022). "MORC2, a newly discovered chromatin remodeling protein, plays an important role in the biological processes of various cancers." (PMID 36234785, 2022). "Despite its functional importance in human cancer, the regulatory mechanism of MORC2 still remains enigmatic." (PMID 34974534, 2022). "MORC2 expression was widely upregulated in most cancer types, and aberrant MORC2 expression predicted the survival of cancer patients." (PMID 36568396, 2022). "Here, our analytic data from TCGA is consistent with the findings of another group that MORC2 is upregulated in most cancers including CRC." (PMID 36234785, 2022).
cancer (continued). "N-acetyltransferase 10 (NAT10) catalyzes the acetylation of MORC2 at K767 and thus promotes DNA damage-induced G2 checkpoint arrest and decreases the sensitivity of cancer cell to DNA-damaging chemotherapy and radiotherapy." (PMID 35216622, 2022). "MORC2 is an emerging oncoprotein that is upregulated in various types of human cancer and contributes to cancer cell growth, metastasis, and chemoresistance." (PMID 34974534, 2022). "We can draw a conclusion that MORC2 inhibits C/EBPα-mediated signal pathway which involves in the switch from a cell differentiation to a cell proliferation program in cancer." (PMID 30644437, 2019). "In summary, these results indicated that MORC2 inhibited C/EBPα-mediated signal, which leads to the switch from a cell differentiation to a cell proliferation program in cancer." (PMID 30644437, 2019). "As expected, C/EBPα suppressed cancer cell growth to a greater extent than vector control, while C/EBPα along with Flag-MORC2 attenuated C/EBPα-mediated cancer cell arrest in SGC-7901 cell lines compared to C/EBPα-K161R plus MORC2." (PMID 30644437, 2019). "It is well documented that MORC2 inhibits the expression of several tumor suppressor genes, and thus promotes cancer progression." (PMID 31180332, 2019). "Collectively, these data indicate that the PGK1/MORC2 axis not only drives radioresistance in PDAC but may exhibit broader relevance in other cancers." (PMID 41213904, 2025). "As a repressor in neural cells, MORC2 may help silence cytostatic adhesion/ECM genes in YAPoff cancers." (PMID 39172021, 2024). "Overall, high expression of MORC2 drives chemotherapy resistance to cancer." (PMID 37692502, 2024). "Some pieces of evidence demonstrated that MORC2 participated in metabolic alterations observed in lipid, glucose, and glutamine metabolism, which support the uncontrolled growth and malignant metastasis of cancer cells." (PMID 37692502, 2024). "It was found that MORC2 expression levels were negatively correlated with the compound activity of PTX, further confirming that high expression of MORC2 could reduce the sensitivity of cancer cells to PTX." (PMID 36967563, 2023). "The expression of MORC2 is induced with high glucose concentration in cancer cells." (PMID 37892209, 2023). "MORC2 expression is very high in cancer cells compared to normal cells." (PMID 37892209, 2023). "Based on these studies, we speculated that MORC2 may affect the sensitivity of cancer cells to PTX and VCR by inhibiting the function of the SAC." (PMID 36967563, 2023). "Moreover, knockout of endogenous MORC2 results in enhanced sensitivity of cancer cells to PTX and VCR." (PMID 36967563, 2023). "It is well known that MORC2 is involved in the control of several cancer-related functions." (PMID 37892209, 2023). "Notably, MORC2 interacts with many proteins to control the expression of its downstream targets, which promote the hallmarks of cancer or directly modulate the hallmarks of cancer by regulating the transcription of its target genes." (PMID 37892209, 2023). "Hence, MORC2 SUMOylation stabilizes the genome and favors cancer cell survival under genotoxic stress." (PMID 36793866, 2023). "We examined the MORC2 mRNA expression in different cancers from the TCGA database." (PMID 36234785, 2022). "Given its emerging roles in tumor progression and in resistance to DNA-damaging radio- and chemotherapies, MORC2 could be a good candidate target for cancer treatment." (PMID 31796101, 2019). "Although, in our study, we used the mouse C2C12 cell line and cancer cell lines to study MORC2 involved in cell differentiation and proliferation, we can draw a conclusion that the over-expression of MORC2 can inhibit cell differentiation and promote cell proliferation." (PMID 30644437, 2019).
cancer (continued). "We, therefore, explored whether MORC2 expression affected on C/EBPα-mediated cell arrest in human cancer." (PMID 30644437, 2019). "In human cancer, MORC2 has been shown to promote gastric tumorigenesis." (PMID 29228664, 2017). "Moreover, we assessed whether a correlation existes between drug activity of PTX/VCR and expression levels of MORC2 using the CellMiner database, which contains drug sensitivity information for 60 cancer cell lines." (PMID 36967563, 2023). "The generation of MORC2 knockout mice, especially MORC2 liver knockout mice, is urgently required to comprehend the functional significance of MORC2 in metabolism and metastasis, as we and other studies reported that MORC2 has a role in glucose, glutamine, and lipid metabolism in cancer." (PMID 37892209, 2023). "However, MORC2 is related to many cancer types, so regulating Morc2a gene expression is critical." (PMID 34695197, 2021). "Recent work has demonstrated that MORC2 may act as an oncogene in several cancer types." (PMID 31180332, 2019). "We suggest that MORC2 may be a potential therapeutic target in cancer." (PMID 26098774, 2015). "Therefore, our data suggest that the MORC2 phosphorylation may play a critical role in the development of cancer, which may provide an important insight into understand the mechanisms of tumorigenesis and have significant therapeutic implications." (PMID 25888627, 2015). "In ER-positive breast cancer, estrogen-mediated MORC2 phosphorylation via the GPER1 pathway inhibits chaperone-mediated autophagy, leading to increased MORC2 protein expression and promoting cancer cell proliferation and metastasis." (PMID 40760337, 2025). "MORC2, a GHKL-type ATPase, is overexpressed in various human tumors and has significant impacts on cancer aggressiveness, treatment resistance, and clinical outcomes." (PMID 39247603, 2024). "It is well documented that MORC2 inhibits the transcription of several target genes, such as CAIX, ArgBP2, p21Waf/Cip1, and thus promotes cancer progression." (PMID 39048555, 2024). "MORC2, a MORC family member, is considered as an oncogenic protein because it is highly expressed in cancers and promotes the migration, invasion, and metastasis of cancer cells." (PMID 39329063, 2024). "Overall, these discoveries reveal the novel function and related molecular mechanism of MORC2 in regulating SAC activation, mitotic progression and resistance of cancer cells to MTA‐based chemotherapy." (PMID 36967563, 2023). "In the cytoplasm, MORC2 interacts with adenosine triphosphate (ATP)-citrate lyase (ACLY) to promote lipogenesis and cholesterogenesis in cancer." (PMID 37892209, 2023). "We report here for the first time that MORC2 knockout contributes to PTX‐ and VCR‐induced mitotic arrest and enhances cancer cellular sensitivity to these MTAs." (PMID 36967563, 2023). "Further, MORC2 interacts with EZH2 or HSF1 to control the expression of ArgBP2, which promotes the proliferation, invasion, and migration of cancer cells." (PMID 37892209, 2023). "Here, we identified microrchidia family CW‐type zinc finger 2 (MORC2), a poorly characterized oncoprotein, as a novel regulator of SAC activation, mitotic progression, and resistance of cancer cells to PTX and VCR." (PMID 36967563, 2023). "Based on the documented functions of these genes in human cancer, we selected SNAIL and CTGF for further validation by qPCR assays in MORC2-KO BT549 and MCF-7 cells reconstituted with empty vector pMSCV, WT or T556A mutant MORC2." (PMID 34974534, 2022). "To evaluate the pan-cancer relevance of this mechanism, we assessed whether PGK1-mediated phosphorylation of MORC2 at S711 promotes radioresistance beyond PDAC." (PMID 41213904, 2025).